ATG16L2 (autophagy related 16 like 2)
Description:
May play a role in regulating epithelial homeostasis in an ATG16L1-dependent manner.
Synonyms: WDR80; FLJ00012; ATG16B
Tractability: No criterion of Open Targets' tractability assessment is met for any kind of drug.
Gene: Protein-coding gene on chromosome 11 (72,814,138 to 72,843,674, forward strand). Ensembl gene ENSG00000168010.
Subcellular location: Cytoplasm, cytosol
Subcellular location (Human Protein Atlas): Nucleoplasm
Pathways (Reactome):
Autophagy: Macroautophagy
Gene Ontology:
Biological process: autophagosome assembly; autophagy
Cellular component: Atg12-Atg5-Atg16 complex; nucleoplasm; autophagosome; cytosol
Genetic constraint (gnomAD): Loss-of-function variants: 74 observed, 76.37 expected, observed/expected ratio (o/e) 0.97, 90% interval 0.8 to 1.18. The upper end of that interval is the gene's LOEUF score, 1.18, which puts it in group 5 of 6, group 1 being the genes least tolerant of losing a copy. Missense variants: 780 observed, 763.09 expected, observed/expected ratio (o/e) 1.02, 90% interval 0.96 to 1.08. Synonymous variants: 361 observed, 315.86 expected, observed/expected ratio (o/e) 1.14, 90% interval 1.05 to 1.25.
Homologues: Orthologues: chimpanzee ATG16L2 (99% identical), macaque ATG16L2 (92% identical), pig ATG16L2 (85% identical), guinea pig ATG16L2 (84% identical), dog ATG16L2 (83% identical), mouse Atg16l2 (83% identical), rat Atg16l2 (82% identical), rabbit ATG16L2 (80% identical), tropical clawed frog atg16l2 (40% identical), Drosophila melanogaster Atg16 (29% identical), Caenorhabditis elegans atg-16.2 (22% identical), Caenorhabditis elegans atg-16.1 (21% identical). Paralogues in human: ATG16L1 (37% identical).
Diseases named in the same sentence as ATG16L2 in open-access papers:
ATG16L2 is named in the same sentence as 42 diseases in open-access papers, as found by Europe PMC text mining. Sharing a sentence is not in itself a finding about the gene and the disease. The quoted sentences say what the papers report.
breast carcinoma (4 papers, 2017 to 2021). "However, few studies could perfectly explain the role of BAX and ATG16L2 in breast cancer treatment resistance." (PMID 33796128, 2021). "The results showed that some of the genes related to the prognosis of breast cancer (IKBKB, ATG16L2, CLN3, MBTPS2, TSC2, and CAPN10) had a higher frequency of mutations." (PMID 34457116, 2021). "Silencing BAG1 in breast cancer cells increases resistance to tamoxifen and reduces apoptosis by activating the PI3K/Akt/mTOR signaling pathway, and the overexpression of ATG16L2 is related to poor prognosis in epithelial cancer." (PMID 32547955, 2020). "Most importantly, there are several genes that can distinguish the four breast cancer subtype as specific therapeutic targets for each subtype, including EFCAB2 for luminal A, ATG16L2 for luminal B, C1QTNF6 and NDUFS6 for HER2+, as well as CHERP, TIAM1, and GABRP for TNBC." (PMID 28245581, 2017).
mastitis (3 papers, 2018 to 2021). Inflammation of breast tissue during lactation or postpartum due to an obstructed duct or infection. "The SNP rs110414316 on BTA15, an intron variant and in significant association with recoverability from mastitis in the full dataset is located in a protein coding gene ATG16L2 (autophagy related 16 like 2)." (PMID 29755506, 2018). "It is reported that the gene Atg16l2 (autophagy related 16 like 2) influences the adaptation of the immune system to the recovery from mastitis in Danish Holstein cattle." (PMID 33552127, 2020).
colon cancer (2 papers, 2019 to 2021). "ATG16L2 have been found to be prognostic marker for clear-cell renal cell carcinoma and stages I-III colon cancer." (PMID 34809598, 2021).
glioma (2 papers, 2019 to 2023). A benign or malignant brain and spinal cord tumor that arises from glial cells (astrocytes, oligodendrocytes, ependymal cells). "For example, autophagy-related genes, including ULK1, ATG10, and ATG16L2, possess a prognostic value in glioma cohorts and were used as the biomarkers in diagnosing glioma." (PMID 37182147, 2023).
kidney cancer (2 papers, 2020 to 2021). Primary or metastatic malignant neoplasm involving the kidney. "This also brought us new thinking about the roles of BAG1 and ATG16L2 in kidney cancer." (PMID 32780567, 2020).
lung cancer (2 papers, 2019 to 2021). A malignant neoplasm involving the lung. "Compared with normal tissues, the expression of ADM2, CLIC6, KIF20A, LAD1, MUC5B, and TNS4 was up-regulated, and the expression of ATG16L2, KCNK3, MAFF, NKD1, and SPATA13 was down-regulated in lung cancer tissues." (PMID 34804921, 2021).
melanoma (2 papers, 2021 to 2023). A malignant, usually aggressive tumor composed of atypical, neoplastic melanocytes. "Transcriptomic data and real‐time PCR analysis demonstrated reduced expression of autophagy related 16 like 2 (ATG16L2) in TRAF6‐deficient melanoma cells." (PMID 37484971, 2023). "The expression level of Autophagy Related 16 Like 2 (ATG16L2) was decreased in TRAF6‐deficient melanoma cells." (PMID 37484971, 2023). "Since cinchonine was reported as a TRAF6 inhibitor and was found to induce apoptosis and autophagy, the inhibitory role of cinchonine in melanoma cells might be associated with the ATG16L2 pathway." (PMID 37484971, 2023). "Taken together, our results indicate that the TRAF6/c‐Jun/ATG16L2 signaling axis plays an essential role in the crosstalk between apoptosis and autophagy in melanoma." (PMID 37484971, 2023). "In this study, we present evidence supporting the role of TRAF6 in the downregulation of ATG16L2 through c‐Jun, which ultimately triggers both apoptosis and autophagy in melanoma cells." (PMID 37484971, 2023). "We next found that cinchonine, a TRAF6 inhibitor, suppressed melanoma tumor growth by enhancing autophagy and leading to apoptosis through the c‐Jun/ATG16L2 pathway." (PMID 37484971, 2023). "The level of autophagy was evaluated by TEM, and numerous phagosomes were observed in ATG16L2‐knockdown melanoma cells." (PMID 37484971, 2023). "Since we found a significant change in ATG16L2 expression in TRAF6‐knockdown melanoma cells, further investigation of the role of ATG16L2 was deemed highly important." (PMID 37484971, 2023). "Taken together, these results indicated that cinchonine inhibited the growth of melanoma cells through the TRAF6/c‐Jun/ATG16L2 signaling pathway." (PMID 37484971, 2023). "Our findings highlight the therapeutic potential of targeting the TRAF6‐c‐Jun/ATG16L2 axis in melanoma treatment." (PMID 37484971, 2023). "Here, we found that suppressing ATG16L2 expression led to elevated apoptosis and autophagy in melanoma cells." (PMID 37484971, 2023). "Next, we tried to determine the function of ATG16L2 in melanoma cells." (PMID 37484971, 2023). "Treatment with 150 μM of cinchonine notably decreased the level of ATG16L2 in melanoma cells." (PMID 37484971, 2023). "Additionally, we show for the first that ATG16L2 is implicated in autophagy and is regulated by the TRAF6/c‐Jun pathway in melanoma cells." (PMID 37484971, 2023). "Therefore, we knocked down ATG16L2 in melanoma cell lines, including SK‐Mel‐5 and SK‐Mel‐28." (PMID 37484971, 2023). "Here, we found that TRAF6 participates in the survival pathway in melanoma cells through ATG16L2, and our previous studies demonstrated that TRAF6 promotes the malignant phenotype of melanoma cells." (PMID 37484971, 2023). "In this study, we demonstrated that TRAF6 modulated the expression of c‐Jun/ATG16L2, and that knocking down either TRAF6 or ATG16L2 induced apoptosis in melanoma cells." (PMID 37484971, 2023). "The results confirmed that APOL1 have higher expression in GSE46517 while ATG16L2, DAPK2, ATG9B and EGFR have lower expression in GSE15605 for primary melanoma compared with normal skin." (PMID 34809598, 2021). "Importantly, targeting TRAF6 with cinchonine, a TRAF6 inhibitor, effectively suppressed the growth of melanoma cells by inducing autophagy and apoptosis through the TRAF6/c‐Jun/ATG16L2 signaling pathway." (PMID 37484971, 2023).
Alzheimer disease (1 paper, 2023). A progressive, neurodegenerative disease characterized by loss of function and death of nerve cells in several areas of the brain leading to loss of cognitive function such as memory and language. "The aim of this study was to further investigate the role of genes identified in our previous studies as relevant for the pathophysiology of Alzheimer’s disease and T2DM comorbidity, namely ATG16L1, ATG16L2, GABARAP, GABARAPL1, GABARAPL2, and SQSTM1." (PMID 36901549, 2023).
astrocytoma (1 paper, 2015). "Hypermethylation of five autophagy-related genes, BECN-1, ATG16L2, ULK2, BNIP3 and a variant of LC3A, were previously reported respectively in BC, leukemia, astrocytoma, colorectal cancer and esophageal carcinoma and these data demonstrated that this hypermethylation was correlated to tumor grade." (PMID 26474850, 2015).
autoimmune disease (1 paper, 2019). A disorder resulting from loss of function or tissue destruction of an organ or multiple organs, arising from humoral or cellular immune responses of the individual to their own tissue constituents. "The reported associations with autoimmune diseases suggest the possibility that Atg16l2 may also perform a specific function in the regulation of immune responses." (PMID 30850634, 2019).
bipolar disorder (1 paper, 2024). A disorder of the brain that causes unusual shifts in mood, energy, activity levels and the ability to carry out day-to-day tasks. "Previous studies of RNA expression in the postmortem brains of patients with MDD and bipolar disorder have shown alterations in the expression of lysosome‐related genes, including MCOLN1 and ATG16L2." (PMID 39264289, 2024).
cervical cancer (1 paper, 2021). A primary or metastatic malignant neoplasm involving the cervix. "Consistent with our hypothesis, ZBTB28 could directly activate the FIP200 and ATG16L2 wild-type promoter activities in 293 T and cervical cancer cells, however it was incapable of activating the promoters of mutant one." (PMID 33931087, 2021).
Cirrhosis (1 paper, 2012). A chronic disorder of the liver in which liver tissue becomes scarred and is partially replaced by regenerative nodules and fibrotic tissue resulting in loss of liver function. "ATG16L2, DEFB114, FAM14B, IFNA21, IL8RB and KIR2DL genes were up-regulated in cirrhosis, whereas, FCRL3, IFITM2 and OAS2 genes were up-regulated in initial fibrosis." (PMID 22397681, 2012).
Crohn disease (1 paper, 2023). A gastrointestinal disorder characterized by chronic inflammation involving all layers of the intestinal wall, noncaseating granulomas affecting the intestinal wall and regional lymph nodes, and transmural fibrosis. "Data showing its relevance in serious diseases such as Crohn’s disease and various cancers notwithstanding, very incomplete information is available on the role of Atg16L2." (PMID 36901549, 2023).
dermatitis (1 paper, 2023). An inflammatory process affecting the skin. "Other cell signaling pathways including cell cycle and NF-kB pathway (CCND1), autophagy (ATG16L2, ATG10), wnt/β-catenin (APC, GSK3β) and angiogenesis (EDN1) regulating genes were associated with RT related acute mucositis and dermatitis." (PMID 37954025, 2023).
diffuse gastric adenocarcinoma (1 paper, 2021). An adenocarcinoma arising from the stomach. "Four DEGs including ATG10, ATG16L2, ULK4 and GABARAPL1 showed differences in diffuse gastric adenocarcinoma subgroup, while other four DEGs including ATG7 (probe 224025_s_at), GABARAPL1, WIPI2 and GABARAPL3 showed differences in gastric intestinal type adenocarcinoma subgroup." (PMID 33604190, 2021).
Insulin resistance (1 paper, 2023). Increased resistance towards insulin, that is, diminished effectiveness of insulin in reducing blood glucose levels. "Similar to findings obtained in 3xTg-AD mice, in the presence of insulin resistance, Atg16L1, Atg16L2, and GabarapL1 expression levels were significantly increased." (PMID 36901549, 2023). "Significantly elevated expression of Atg16L1, Atg16L2, and GabarapL1 was also observed in H4Swe cell cultures, in the presence of insulin resistance." (PMID 36901549, 2023). "Similar to findings in 3xTg-AD mice, we found that Atg16L1, Atg16L2, and GabarapL1 were significantly elevated in insulin resistance conditions." (PMID 36901549, 2023).
lung adenocarcinoma (1 paper, 2017). A carcinoma that arises from the lung and is characterized by the presence of malignant glandular epithelial cells. "ATG10 rs10036653, ATG12 rs26538, ATG16L1 rs2241880 and ATG16L2 rs11235604 were significantly associated with OS of gefitinib-treated advanced lung adenocarcinoma patients (all P < 0.05)." (PMID 29259263, 2017). "We found that ATG10 rs10036653, ATG12 rs26538, ATG16L1 rs2241880 and ATG16L2 rs11235604 were significantly associated with survival of lung adenocarcinoma patients (all P < 0.05)." (PMID 29259263, 2017).
neuroblastoma (1 paper, 2021). Neuroblastoma (NB) is the most common solid, extracranial childhood tumor. "It was shown that knocking down Atg16l2 in human neuroblastoma H4 cells resulted in increased autophagy flux, suggesting the negative regulation of autophagy by Atg16l2." (PMID 34458256, 2021).
non-small cell lung carcinoma (1 paper, 2022). A group of at least three distinct histological types of lung cancer, including non-small cell squamous cell carcinoma, adenocarcinoma, and large cell carcinoma. "Patients who suffer from non-small-cell lung cancer (NSCLC) with high ATG16L2 expression have a better prognosis after radiotherapy." (PMID 35645767, 2022).
pneumonitis (1 paper, 2021). An inflammatory process affecting the lung parenchyma. "Potentially functional ATG16L2 variants foretell radiation outcomes and pneumonitis in NSCLC patients after radiotherapy." (PMID 34518802, 2021).
retinitis pigmentosa (1 paper, 2025). Retinitis pigmentosa (RP) is an inherited retinal dystrophy leading to progressive loss of the photoreceptors and retinal pigment epithelium and resulting in blindness usually after several decades. "Dysregulation of ATG16L2, due to mutations or altered expression, can lead to autophagic dysfunction, which is implicated in a range of disorders, including AMD and retinitis pigmentosa." (PMID 40771354, 2025).
Stroke (1 paper, 2023). Sudden impairment of blood flow to a part of the brain due to occlusion or rupture of an artery to the brain. "The implication of ATG12 and ATG16L2 in the inhibition of inflammation might indicate a reduction of inflammatory responses in CE stroke, which was involved with autophagy." (PMID 37305740, 2023). "The remaining autophagy-related genes, such as ATG12, ATG16L2, ATG2B, and BECN1 were also significantly increased in CE strokes while not all types of strokes." (PMID 37305740, 2023).
Zika virus infection (1 paper, 2017). "ATG16L2 (Autophagy related 16-like 2) was identified among the top 30 down-regulated genes in human neural stem cells after the Zika virus infection." (PMID 28932709, 2017).
tumor (7 papers, 2010 to 2023). "As a molecular marker of tumor behavior and prognosis, ATG16L2 is associated with KIRC risk and patient outcome." (PMID 33679977, 2021). "Immunohistochemistry was then performed on tumor slices to investigate the role of cinchonine in the expression of TRAF6, c‐Jun, and ATG16L2 in tumor tissue." (PMID 37484971, 2023). "Some researchers have used the expression level of ATG16L2 to detect the response of cells to cisplatin, speculating that it may be a biomarker for tumor cells resistant to platinum-based drugs." (PMID 34636718, 2021). "The fact that ATG5 is selectively inactivated by somatic mutations and/or alternative mRNA splicing, and that ATG16L2 is transcriptionally overexpressed, relative to ATG16L1, in multiple tumor types, suggests that the inhibition of autophagy is indeed oncogenic." (PMID 31636955, 2019). "However, statistically significant increases in ATG16L2 expression were observed, relative to ATG16L1, in 5 out of the 12 tumor types analyzed (p < 0.01)." (PMID 31636955, 2019). "Since either upregulation of ATG16L2 expression or downregulation of ATG16L1 expression in human tumors should increase the competitive binding of ATG16L2 to ATG5, we calculated the ATG16L2:ATG16L1 mRNA expression ratio in normal and tumor samples from the TCGA mRNA datasets." (PMID 31636955, 2019). "To understand the mechanism of this differential effect, we found that ferroptosis inducers upregulate mRNAs encoding multiple direct and indirect autophagy stimulators, such as ATG16L2, ATG9A, ATG4D, GABARAP, SQSTM/p62, SEC23A and BAX, in tumor cells growing in 2D but not in 3D culture." (PMID 37658069, 2023).
cancer (4 papers, 2019 to 2023). A tumor composed of atypical neoplastic, often pleomorphic cells that invade other tissues. "Finally, we provide evidence that ATG16L2, which is overexpressed in several cancers relative to ATG16L1, hijacks the conjugation switch by competing with ATG16L1 for binding to ATG5." (PMID 31636955, 2019). "ATG16L2 is located on chromosome 11 and has not been studied in relation to cancer." (PMID 31626592, 2019).
infection (4 papers, 2009 to 2023). The state of being infected such as from the introduction of a foreign agent such as serum, vaccine, antigenic substance or organism. "There were no marked changes noted in the expression of Becn1, Atg5, Atg7, Atg12, Atg16l1 or Atg16l2 both before and 6 h after infection." (PMID 35903351, 2022). "Beclin1/ATG6, ATG4A, 5, 12, and ATG16L2 have previously shown to be differentially expressed during infection with the intracellular pathogen Francisella tularensis." (PMID 27302320, 2016). "This notion is supported by evidence showing that intracellular infection with Francisella down-regulates several autophagy-related genes in THP-1 human monocytes, including ATG5, ATG12, ATG16L2, ATG7, ATG4A and class III PI3K." (PMID 20003180, 2009).
bacterial infection (1 paper, 2016). "The array analysis revealed that many autophagy related mRNAs (i.e., LC3-II, Atg4C, and Atg16L2) were upregulated in macrophages, suggesting that autophagy may be involved in bacterial infection." (PMID 26735693, 2016).
ATG16L2 also shares sentences with these, for which no sentence is quoted: basal cell carcinoma (1 paper); breast tumors (1); brucellosis (1); clear-cell renal cell carcinoma (1); colorectal cancer (1); diabetes (1); esophageal carcinoma (1); gastric intestinal type adenocarcinoma (1); leukemia (1); maturity onset diabetes (1); myelosuppression (1); Obesity (1); oral mucositis (1); radiation pneumonitis (1).